PTX3 (pentraxin 3)
Diseases named in the same sentence as PTX3 in open-access papers (continued):
Sharing a sentence is not in itself a finding about the gene and the disease.
liver disease (10 papers, 2013 to 2025). "In the context of hepatic disorders, circulating PTX3 has been implicated in the pathophysiology of non-alcoholic steatohepatitis (NASH)." (PMID 41462970, 2025). "PTX3 encodes pentraxin 3, a well-recognised biomarker for inflammatory conditions including liver disease, which is involved in complement activation, angiogenesis, and tissue remodelling." (PMID 37373054, 2023). "In liver pathology, the detection of an elevated blood concentration of PTX3 is an index of hepatic disease." (PMID 34680561, 2021). "In liver diseases, PTX3 levels were markedly higher in NASH than in simple steatosis non-NASH patients." (PMID 33219288, 2020). "The combination of PTX3 with AFP may allow further identification of HCC in the HBV-related liver disease population." (PMID 33219288, 2020). "Recently, PTX3 has been used as a biomarker of liver diseases." (PMID 28912805, 2017). "In addition, PTX-3 is important for diagnosing liver disease." (PMID 35059041, 2021). "Moreover, this study showed that the addition of PTX3 to AFP may allow further identification of HCC in the HBV-related liver diseases." (PMID 33219288, 2020). "A number of these analytes were differentially expressed related to liver disease, including proteins with inflammatory and immunomodulatory activities, such as CCL15, pentraxin-3, TRAIL and MMP-3, among others, as well as the growth factors M-CSF, SCF, SCFG-β and HGF." (PMID 36230823, 2022). "Similarly to HGF, it might well be that these discrepancies are due to the multiple functions of PTX3 on the one hand and also the different etiologies of liver disease, i.e. non-focally distributed NASH compared to focally distributed CFLD, on the other hand." (PMID 23516586, 2013).
unstable angina (10 papers, 2011 to 2024). "PTX3 is expected to be a marker for ischemic heart disease such as unstable angina and myocardial infarction." (PMID 39802992, 2024). "Circulating levels of PTX3 are known to be elevated in patients with unstable angina and are thought to play an important role in the formation of unstable plaques, particularly in coronary arteries." (PMID 39802992, 2024). "Several clinical studies have reported elevated plasma PTX3 levels in patients following acute MI or unstable angina." (PMID 24705587, 2014). "Patients with unstable angina pectoris have higher PTX3 levels than healthy controls, suggesting that this long pentraxin might be a candidate marker to unstable angina." (PMID 31057548, 2019). "Similarly, in patients with angina who underwent PCI, PTX3 levels resulted to be an independent risk factor associated to troponin increase after PCI." (PMID 31057548, 2019). "In addition PTX3 plasma levels are elevated in patients with unstable angina and in patients undergoing stenting, suggesting that PTX3 is a candidate for being new prognostic marker in ischemic heart disorders." (PMID 21776288, 2011).
Hyperglycemia (9 papers, 2017 to 2025). An increased concentration of glucose in the blood. "The observed mitigation of hyperglycemia in PTX3-deficient mice treated with STZ suggests a critical involvement of PTX3 in the regulation of glucose homeostasis." (PMID 39657836, 2025). "In logistic regression analyses, higher baseline levels of ST2, IL-1ra, PCT, PTX-3, and Ang-2 were associated with higher risk of hyperglycemia in the first two days of ICU admission in both unadjusted and adjusted analyses." (PMID 33755703, 2021). "Additionally, higher baseline ST2, IL-1ra, procalcitonin, and pentraxin-3 levels were associated with increased risk of hyperglycemia." (PMID 33755703, 2021). "The findings presented in this study shed light on the pivotal role of PTX3 in the pathogenesis of hyperglycemia, pancreatic ER stress, and β-cell apoptosis." (PMID 39657836, 2025). "Taken together, these data indicate that deficiency of PTX3 suppresses ameliorates STZ-induced pancreatic islet damage, ultimately reducing hyperglycemia." (PMID 39657836, 2025). "To determine the role of PTX3 in the pathogenesis of hyperglycemia, we first examined if PTX3 affects hyperglycemia and pancreatic β-cell death in an STZ–induced mouse model of T1D." (PMID 39657836, 2025). "In conclusion, this study provides compelling evidence implicating PTX3 in the pathogenesis of hyperglycemia, pancreatic ER stress, and β-cell apoptosis." (PMID 39657836, 2025). "Such lack of consistency is likely due to high variability in the plasmatic concentration of PTX3 in diabetic patients, as a reflection of varying extents of hyperglycemia-dependent damage to tissues and vascular beds." (PMID 35069222, 2021). "Our results suggest associations between the host immune response and hyperglycemia in critically ill septic patients particularly implicating the interleukin-1 axis (IL-1ra), the interleukin-33 axis (ST2), and the host response to bacterial infections (procalcitonin, pentraxin-3)." (PMID 33755703, 2021). "However, the precise role of PTX3 in hyperglycemia remains unclear." (PMID 39657836, 2025). "We propose that PTX3 is involved in the local rather than systemic inflammatory reaction to hyperglycemia." (PMID 35069222, 2021).
mastitis (9 papers, 2012 to 2025). Inflammation of breast tissue during lactation or postpartum due to an obstructed duct or infection. "In the examined Holstein and Montbéliarde dairy cows, single nucleotide polymorphisms (SNPs) and gene expression profile changes related to mastitis resistance/susceptibility were found in the PTX3 gene." (PMID 40559821, 2025). "Staphylococcus aureus, one of the main causes of mastitis, was discovered to cause an upregulation of PTX3." (PMID 36669036, 2023). "The SNP rs109126926 on BTA1, an intron variant and in significant association with recoverability from mastitis in parity 2, is located within a protein coding gene PTX3 (pentraxin 3)." (PMID 29755506, 2018). "PTX3 showed a large change in expression in both milk and blood, and is therefore a candidate for further studies on immune response associated with mastitis." (PMID 23046560, 2012). "Genes involved in lymphocyte developments (e.g., MAST3 and STAB2) and genes involved in macrophage recruitment and regulation of inflammations (PDGFD and PTX3) were suggested as possible causal genes for susceptibility to – and recoverability from mastitis, respectively." (PMID 29755506, 2018). "PTX3 had the higher log fold change in expression in both in milk and in blood and is a candidate for further studies on the genetic basis of variations to in immune response associated with mastitis." (PMID 23046560, 2012). "The differentially expressed genes in bovine lymphocytes regulated by H3K27me3 on upstream 2 kb regions (IL10, PTX3 and etc.)may relate to S. aureus mastitis susceptibility and could be considered as key candidate genes for anti- S. aureus mastitis study and breeding." (PMID 27503467, 2016). "PTX3 has been found in bovine, ovine and caprine mastitis milk and the expression of its encoding gene by MEC is increased in response to infection by mastitis-associated pathogens." (PMID 30045763, 2018). "For recoverability from mastitis we suggest EPS15L1 (essential for lymphocyte development), PDGFD (involves in macrophage recruitment and wound healing), and PTX3 (involved in regulating inflammation) as candidates for the causal genes." (PMID 29755506, 2018). "Concomitantly with the early induction of cytokine and chemokine-encoding genes, we identified an up-regulation of two genes coding for acute phase proteins (APP): pentraxin 3 (PTX3) and α-1 anti-proteinase (SERPINA1) which were also found in bovine milk at the beginning of mastitis." (PMID 24521038, 2014).
Shock (9 papers, 2014 to 2025). The state in which profound and widespread reduction of effective tissue perfusion leads first to reversible, and then if prolonged, to irreversible cellular injury. "We found that plasma PTX3 levels were associated with septic shock, renal replacement therapy, amputation and risk of death in patients with NSTI." (PMID 26880104, 2016). "Generally speaking, in studies high levels of PTX3 have been associated with an unfavourable outcome (and increased mortality) and PTX3 was elevated in systemic inflammatory response syndrome and septic shock." (PMID 36574434, 2022). "In septic shock patients, both the initial and follow-up PTX3 levels were consistently significantly higher in patients who died than in those who recovered (initial p = 0.004; follow-up P < 0.001)." (PMID 31718563, 2019).
colitis (8 papers, 2020 to 2025). Inflammation of the colon. "Plasma PTX-3 levels were 1.25 ± 0.19 ng/mL in the control group and increased to 2.51 ± 0.30 ng/mL in the colitis + saline group (** p < 0.01; p = 0.001), indicating an acute-phase inflammatory response." (PMID 40572721, 2025). "As inhibitors specific to PTX3/Ptx3 activity are not available, we turn to use IL1R1-specific inhibitor anakinra to assess the function of Ptx3 in the TedCH, colitis, and aberrant hematopoiesis." (PMID 40230417, 2025). "Suramin treatment reduced PTX3 concentrations to 1.4 ± 0.2 ng/mL, with a significant difference from the colitis group (# p < 0.01), suggesting reduced tissue stress." (PMID 40428786, 2025). "Elevated PTX3 levels have been reported in acetic acid-induced colitis models, supporting its involvement in the acute inflammatory response." (PMID 40572721, 2025). "Our findings demonstrate that Indoximod significantly reduced colonic TLR4 expression and plasma levels of TNF-α and PTX3 while also improving histopathological damage in rats with acetic acid-induced colitis." (PMID 40572721, 2025). "To guarantee that PTX3/IL-1β signaling is involved in human colitis or leukemia, we searched publicly available datasets of bulk RNA-seq or scRNA-seq and compared their expression between the disease group and healthy controls." (PMID 40230417, 2025). "Plasma tumor necrosis factor alpha, Pentraxin 3, and malondialdehyde levels were significantly lower in the calcitriol administered colitis group than in the standard colitis group (p<0.01)." (PMID 32555936, 2020). "Plasma PTX3 levels also increased significantly in the colitis and saline group (P < 0.001) while decreased in the adenosine treated rats with colitis (P < 0.05)." (PMID 32074166, 2020). "Additionally, analysis of colitis samples suggests that higher expression of PTX3 and IL-1β took place in some cohorts of colitis samples compared with the controls." (PMID 40230417, 2025). "Collectively, these results provide a solid experimental foundation indicating that suramin may effectively alleviate acute colitis by suppressing the TNF-α/NET/PTX3 axis and reducing ROS-mediated tissue injury." (PMID 40428786, 2025). "Suramin treatment significantly reduced plasma PTX3, TNF-α, NETs, and MDA levels, and colonic TNF-α and VEGF concentrations compared to the untreated colitis group." (PMID 40428786, 2025). "As expected, the induction of acute colitis resulted in elevated levels of proinflammatory mediators such as TNF-α, PTX3, and PAF in plasma and TLR4 in colon tissue." (PMID 40572721, 2025). "Suramin administration decreased the severity of colitis; this effect was supported by decreased serum TNF-α, NETs, PTX3, and MDA levels and suppressed TNF-α and VEGF levels in colonic tissue." (PMID 40428786, 2025). "According to the results, plasma TNF-α, PTX-3 and MDF levels were significantly increased in the colitis + saline group compared to the normal control group (p<0.05, p<0.001, and p<0.001, respectively; p< 0.001, p<0.001, and p<0.001 respectively)." (PMID 35894303, 2022). "Increased levels of tumor necrosis factor-α (TNF-α), pentraxin-3, and malondialdehyde (MDA) in colitis group were revealed biochemically." (PMID 36228298, 2022). "The levels of TNF-α, PTX-3, and MDA were measured in plasma samples, and there was significant increase in colitis group." (PMID 36228298, 2022).
esophageal squamous cell carcinoma (8 papers, 2019 to 2025). Esophageal squamous cell carcinoma (ESCC) is a type of esophageal carcinoma (EC) that can affect any part of the esophagus, but is usually located in the upper or middle third. "Studies have shown that PTX3 expression is suppressed in esophageal squamous cell carcinoma (ESCC) due to promoter hypermethylation." (PMID 41479916, 2025). "PTX3 expression has been shown to be downregulated in a large proportion of esophageal squamous cell carcinomas." (PMID 34048179, 2021). "In addition, epigenetic studies showed promoter hypermethilation and silencing of PTX3 expression in selected human tumors, such as colorectal cancer and esophageal squamous cell carcinoma." (PMID 37025408, 2023).
pulmonary arterial hypertension (8 papers, 2012 to 2025). Pulmonary arterial hypertension (PAH) is a group of diseases characterized by mean pulmonary artery pressure >20 mmHg and elevated pulmonary arterial resistance leading to right heart failure. "In pulmonary arterial hypertension, PTX3 has been proposed as a more specific and sensitive biomarker compared with brain natriuretic peptide, which so far, was considered the gold standard marker for pulmonary hypertension." (PMID 27559355, 2016). "It should be noted, however, that elevated PTX3 levels have been observed in conditions other than pulmonary hypertension and careful interpretation of the data is required." (PMID 25412085, 2014). "•Plasma IL-6 & PTX3 were elevated in left heart failure and pulmonary hypertension." (PMID 38560419, 2022). "It was reported that PTX-3 could be used as a biomarker in multiple types of pulmonary hypertension (PH), including idiopathic PH, connective tissue disease-associated PH, PH associated with congenital heart disease, and chronic thromboembolic PH." (PMID 30992732, 2019). "We speculated that PTX3 levels may be able to detect the early stage of CTEPH with inflammation before the disease develops to mechanically severe pulmonary hypertension." (PMID 25412085, 2014). "In addition, PTX3 has been recognized as a biomarker for pulmonary arterial hypertension, however whether it is the case in chronic thromboembolic pulmonary hypertension (CTEPH) remains unclear." (PMID 25412085, 2014).
systemic inflammatory response syndrome (8 papers, 2012 to 2023). SIRS is a serious condition related to systemic inflammation, organ dysfunction, and organ failure. "In particular, it has been observed that PTX3 is involved and markedly overexpressed in uncontrolled pathological inflammatory responses like the “systemic inflammatory response syndrome” (SIRS), a severe, dysfunctional, and excessive reaction to noxious stimuli that may ultimately result in sepsis." (PMID 37762499, 2023). "Our goal was to assess PTX3 as a predictor of systemic inflammatory response syndrome (SIRS), death and disease severity in acute pancreatitis (AP) in comparison to C-reactive protein (CRP) and the APACHE II score." (PMID 31798002, 2019).
bacteremia (7 papers, 2011 to 2026). "The present findings evidence the value of PTX3 in patients with blood culture-proven bacteremia caused by the four microbial organisms most commonly encountered in clinical practice." (PMID 21423699, 2011). "The results presented here show high PTX3 values during the first days after diagnosis to be independently associated with case fatality in patients with bacteremia." (PMID 21423699, 2011). "Plasma PTX3 levels were measured in 132 patients with bacteremia caused by Staphylococcus aureus, Streptococcus pneumoniae, β-hemolytic streptococcae and Escherichia coli, using a commercial solid-phase enzyme-linked immunosorbent assay (ELISA)." (PMID 21423699, 2011). "In patients with bacteremia, increased PTX3 levels occur in the acute phase of infection and normalize on recovery; we also found that PTX3 levels in patients with septic shock were initially high but normalized on recovery." (PMID 31718563, 2019). "Systemic levels of PTX3 were significantly higher in patients with blood culture-positive bacteremia compared to healthy controls and blood culture negative samples." (PMID 25530683, 2014). "In one earlier study the maximum PTX3 value on days 1–4 after bacteremia diagnosis was shown to be a predictor of case fatality (d28)." (PMID 23341967, 2013). "In conclusion, PTX3 proved to be a sensitive and specific independent prognostic marker in patients with bacteremia." (PMID 21423699, 2011). "PTX3 measurement offers a novel opportunity for the prognostic stratification of bacteremia patients." (PMID 21423699, 2011). "In a bacteremia study, PTX3 levels were high in the acute phase and normalized on recovery." (PMID 23341967, 2013). "PTX3 proved to be a specific independent prognostic biomarker in bacteremia." (PMID 21423699, 2011). "PTX3 measurement may offer novel opportunities for the early prognostic stratification of bacteremia patients in order to target various therapeutic interventions." (PMID 21423699, 2011). "In contrast, patients with S. aureus bacteremia presented significantly elevated IL-10, IFN-γ, PTX3 and TNF-α levels compared to IC (other) patients." (PMID 33535593, 2021). "Only the day 1–4 values were included in the final ROC analysis, as the PTX3 values on the first days following blood culture (i.e. diagnosis) are most unlikely to be related to conditions other than bacteremia per se." (PMID 21423699, 2011). "In patients with bacteremia, the maximum PTX3 values on days 1–4 were markedly higher in nonsurvivors compared to survivors (44.8 versus 6.4 ng/mL, P < 0.001) and the AUC in the prediction of case fatality was 0.82 (cut-off values 15 ng/mL, sensitivity 72%, and specificity 81%)." (PMID 25530683, 2014).
giant cell arteritis (7 papers, 2014 to 2025). "PTX3 has been proposed to reflect disease activity in small vessel vasculitis and more recently in giant cell arteritis and TA." (PMID 25394473, 2014). "PTX3 may thus be used as a biomarker of actual arteritis in TA." (PMID 25394473, 2014).
kidney damage (7 papers, 2018 to 2025). "Elevated PTX3 levels were associated with diabetic complications, including nephropathy, retinopathy, and cardiovascular diseases." (PMID 40299501, 2025). "In murine models with PTX3 deficiency, it is also shown that PTX3 is important in the natural defense against uropathogens, and this correlates with persistent inflammation and kidney damage." (PMID 36983379, 2023). "In our study, the increase in the amount of PTX3 in the kidney tissue of rats given corn syrup supports the idea that PTX3 increases to create an anti-inflammatory effect in kidney damage." (PMID 39697970, 2024). "As a result of the information obtained, PTX-3 can be used to measure the extent of kidney damage, early evaluation of renal tubule damage, and monitor its clinical progression." (PMID 39697970, 2024). "We observed a positive correlation between lactate dehydrogenase and PTX3 levels, and a weaker yet significant correlation of the platelet count and laboratory signs of kidney damage to PTX3." (PMID 30858847, 2019). "As a result, new biomarkers such as PCX and PTX-3 may be indicators of kidney damage." (PMID 39697970, 2024). "Although technically feasible, we did not consider to recover the wild type mouse nephropathy phenotype by reconstituting the lack of PTX3 in Ptx3-deficient mice by injecting recombinant PTX3 because the PTX3 protein octamer is too large to pass the glomerular filter." (PMID 30319631, 2018). "It was concluded that HT has a protective effect against corn syrup-induced kidney damage, and PCX and PTX-3 may also play a role in this mechanism of action." (PMID 39697970, 2024).